CCL2 (C-C motif chemokine ligand 2)
Diseases named in the same sentence as CCL2 in open-access papers (continued):
Sharing a sentence is not in itself a finding about the gene and the disease.
Cognitive impairment (continued). "In summary, these data implicate that Tan IIA can ameliorate CCL2-induced learning memory and cognitive impairment by impacting oxidative stress and inflammation and finally inhibiting the excessive apoptosis of nerve cells." (PMID 32185196, 2020). "To investigate the protective effect and mechanism of Tanshinone IIA (25, 50, 75 mg/kg/d) on CCL2-induced learning memory and cognitive impairment in rats, we performed the Morris water maze (MWM) and novel object recognition tests (NORT) on the rats." (PMID 32185196, 2020). "Chemokine C–C motif ligand 2 (CCL2) is one of the most widely recognised proinflammatory chemokines in cognitive disorders." (PMID 32103758, 2020). "In this regard, previous reports have indicated that in patients with subtle cognitive impairment, there is an increase in CCL2." (PMID 29723220, 2018). "This scenario would be in line with recent studies demonstrating that an inhibitor of CCL2 synthesis protects neurons against Abeta toxicity and that inhibition of microglial activation reduces cognitive deficits in a transgenic mouse model for AD." (PMID 25666182, 2015). "A 2006 study evaluated CCL2 levels in serum samples from 48 individuals with Mild Cognitive Impairment (MCI), 94 AD patients and 24 age-matched controls." (PMID 25340798, 2014). "While one of the proteins linked to EDII and incident cognitive impairment (CXCL10) has been nominated as a therapeutic target for AD, three candidate proteins (CCL2, CXCL10, and HGF) are therapeutic targets of ongoing clinical trials for non-neurologic disease." (PMID 36737481, 2023). "The MGCs, Mφs, and sera of the PARK2 mouse model displayed decreased expression of parkin and its link to the increased generation of pro-inflammatory cytokines and chemokines (e.g., IFNβ1, TNFα, IL-1β, IL-12, IL-13, IL-17, CCL2, and CXCL1), loss of DA neurons, and cognitive defects in PD." (PMID 34239490, 2021). "Collectively, these data indicated that naringin alleviated the CCL2-induced cognitive impairment." (PMID 32103758, 2020). "Thus, pretreatment with Tan IIA significantly prevented cognitive impairment induced by CCL2 and inhibited the expression of IL-1β and IL-6." (PMID 32185196, 2020). "Thus, this study aimed to explore the neuroprotection afforded by naringin in CCL2-induced cognitive impairment in rats." (PMID 32103758, 2020). "Therefore, the upregulation of CCL2 by IRF7 and its associated molecules may reduce neurodegeneration in the CNS, reducing the cognitive deficits brought upon by HIV-Associated Neurocognitive Disorders (HANDs)." (PMID 36827648, 2023). "Additionally, PARK6-associated PD patients have also shown PINK1 deficiency and its impact on increased generation of pro-inflammatory cytokines and chemokines (e.g., IFNβ1, IL-6, IL-12, IL-13, CCL2, CCL4, and CXCL1), loss of NCs, and the development of cognitive defects." (PMID 34239490, 2021). "Thus, drugs that inhibit or block CCL2-induced cognitive impairment could treat the cognitive dysfunction of HAND patients or improve their learning and memory, which show good prospects for clinical application." (PMID 32185196, 2020). "However, despite the promising results obtained with minocycline in several animal models of inflammatory disorders, pilot studies in HIV-infected individuals have yet to yield significant changes in inflammatory markers such as neopterin, CCL2, or cognitive impairment." (PMID 24732038, 2014). "Prominently, we observed persistently elevated levels of eotaxin/CCL11, CCL2, CCL7, CXCL1, CXCL10 and BAFF in the DIPG, ALL, and aggressive osteosarcoma models, the same three models that also exhibit cognitive deficits." (PMID 38798554, 2024). "In this paper, we review the roles and regulatory mechanisms of pro-inflammatory chemokines (CCL2, CCL3, CCL4, CCL5, CCL11, CCL20, and CXCL8) in cognitive impairment." (PMID 39011039, 2024).
Cognitive impairment (continued). "Indeed, our recent study showed that intrahippocampal injection of CCL2 impaired learning memory and cognition in rats via apoptosis of hippocampal neurons, and rats with CCL2-induced cognitive disorder could be used as an ideal murine model to study the effect of CCL2 on HAND." (PMID 32185196, 2020). "Previously, we demonstrated that Nef increases the expression of macrophage chemokine CCL2 and macrophage marker CD163 which correlate with cognitive deficits observed in our animal model when compared to controls." (PMID 31829243, 2019). "In human genome-wide association studies of prodromal AD and AD patients with mild cognitive impairment (MCI), high amounts of CCL2 were detected in the CSF and CCL2 levels correlated with a faster rate of cognitive decline in the analyzed patient cohort." (PMID 30241479, 2018). "The MCP1/CCL2 protein has been shown to be increased in both CSF and plasma from individuals with mild cognitive impairment (MCI) and AD." (PMID 25540075, 2014). "Hence, it is crucial to investigate the correlation between CCL2 and BBB to better comprehend the mechanisms that contribute to cognitive impairment in NPSLE patients." (PMID 39403387, 2024). "Chemokines CCL1, CCL2, CCL15, CCL27, CXCL9, CXCL10, and CX3CL1 might be most promising to serve as key molecular markers of cognitive impairment, although more cohort studies with larger populations are needed." (PMID 37291639, 2023). "CCL2 (MCP-1) is expressed by neurons, astrocytes, and microglia and has previously been shown to be raised in the CSF of people with typical AD including those with mild cognitive impairment (MCI)." (PMID 34602080, 2021). "We therefore measured the levels of CCL2 and three other CCR2 ligands, i.e. CCL11 (eotaxin), CCL13 (MCP-4) and CCL26 (eotaxin-3), in the cerebrospinal fluid (CSF) and plasma of 30 controls and 119 patients with mild cognitive impairment (MCI) at baseline." (PMID 22303443, 2012).
periodontitis (81 papers, 2012 to 2026). An acute or chronic inflammatory process that affects the tissues that surround and support the teeth. "The genetic association of CCL2 (also known as MCP-1) polymorphism with periodontitis has been a subject of interest in periodontal research." (PMID 37927745, 2023). "Little research has examined the allele, genotype, or haplotype frequencies of CCL2 polymorphisms in people with periodontitis." (PMID 37927745, 2023). "Polymorphisms in the CCL2 gene can influence its expression and function, potentially impacting the development and progression of periodontitis." (PMID 37927745, 2023). "Various chemokine genes located on different chromosomes contribute to periodontitis, and one such gene is C-C motif chemokine ligand 2 (CCL2), associated with the rs1024611 polymorphism, which is part of a cytokine gene cluster on the q-arm of chromosome 17." (PMID 37927745, 2023). "Locally delivered CCL2 prevented alveolar bone loss in a periodontitis mice model due to its ability to decrease macrophage M1:M2 ratio in the gingival tissues, leading to the resolution of inflammation." (PMID 35048045, 2021). "Since MMP-1 and CCL2 are molecules known to be strongly associated with periodontitis, we further studied their regulation by NAMPT." (PMID 24058270, 2013). "These hypotheses drove the current investigation into potential links between CCL2 gene polymorphism and periodontitis." (PMID 37927745, 2023). "Our specific objective was to investigate whether CCL2 polymorphisms could influence the relative risk of developing periodontitis." (PMID 37927745, 2023). "Therefore, we anticipated that CCL2 polymorphisms could influence the relative risk for periodontitis." (PMID 37927745, 2023). "For instance, CCL2 and CCL5 are elevated in gingival crevicular fluid in patients with generalized aggressive periodontitis, and CCL2 is increasingly expressed in fibroblasts from periodontitis patients." (PMID 39781111, 2025). "Monocyte chemoattractant protein 1 (MCP‐1), also known as C‐C motif chemokine ligand 2 (CCL2), is a chemokine crucial for monocyte chemotaxis, endothelial activation and leukocyte function regulation, which are key in inflammation and periodontitis." (PMID 40344491, 2025). "Our results support that CCL2-mediated immunomodulation by the fibroblasts is needed for physiologic response in periodontitis." (PMID 39650645, 2024). "To understand how inflammatory fibroblasts affect macrophage infiltration to the periodontium during induction phase of periodontitis, we examined CCL2, a monocyte and macrophage chemokine that is largely expressed by these fibroblasts." (PMID 39650645, 2024). "ICAM1+ fibroblasts expand in both human periodontitis and murine ligature-induced periodontitis model, which have upregulated expression of CCL2 and CXCL1 compared to other fibroblast populations." (PMID 39650645, 2024). "Inflammatory cytokines, including IL-1β, IL-6, tumor necrosis factor-alpha, and chemokine (C-C motif) ligand 2 (CCL2), play a crucial role in the inflammatory response of periodontitis." (PMID 38560458, 2024). "It has been reported that gingival fibroblasts express cGAS and STING and produce various inflammatory cytokines, including IL-6, IL-8, and CCL2, in periodontitis." (PMID 37405166, 2023). "Our scRNA-seq analysis revealed that macrophages expressed Ccl2, Ccl9, Cxcl4, and Cxcl6, and neutrophils expressed Ccl3, Ccl4, Ccl6, Cxcl2, and Cxcl3 throughout periodontitis development." (PMID 38015204, 2023). "In contrast, patients with aggressive periodontitis were found to have lower levels of other cytokines, including CCL2, M-CSF, GM-CSF, IL-1ra, IL-10, and IL-13." (PMID 38139161, 2023). "As expected, in contrast to untreated periodontitis mice, SR-717-treated mice had elevated CCL2 and CCR2 levels, while SN-011-treated mice had decreased levels." (PMID 37405166, 2023).
periodontitis (continued). "Our results showed that gavage of periodontitis saliva increased the expression of inflammatory factors, including Il-1β, Tnf-α, Cxcl1, Cxcl2, and Ccl2, in the ischemic brain in mice." (PMID 35663549, 2022). "Another study identified CCL2, CCL11, years of smoking, and age as periodontitis associated factors." (PMID 36013449, 2022). "Of note, although human periodontitis was associated with elevated IL-ß expression and MDSC recruitment, LPS appreciably only induced CCL5 and CCL2 in human gingival fibroblasts." (PMID 31685946, 2020). "The cluster of mediators susceptible to inhibition by I-BET151 and JQ1 in gingival fibroblasts and GECs includes IL-6, IL-1β, and CCL2, elevated levels of which are most commonly found in patients with periodontitis." (PMID 33256844, 2020). "The degree of suppression of IL8, IL1B, CCL2, CCL5, MMP3, and COX2 caused by I-BET151 or JQ1 in P. gingivalis-infected GFs from periodontitis patients was comparable to that observed in healthy donor GFs." (PMID 31114581, 2019). "Supporting the protective role of Rothia aeria, a study in periodontitis patients revealed a positive correlation between its abundance and salivary CCL2 levels; CCL2 mitigates inflammation by reducing the M1:M2 macrophage ratio in gingival tissue and prevents alveolar bone loss in murine models." (PMID 41471248, 2025). "Additionally, CCL2 is involved in T-cell immunity, and its high expression can be detected at sites of periodontitis." (PMID 38560458, 2024). "In contrast, neutrophils and macrophages are the major immunocyte infiltration in murine experimental periodontitis, where CCL2 expression by this fibroblast subset may be the most necessary." (PMID 39650645, 2024). "Our research revealed no significant variation in the frequency of CCL2 polymorphism genotypes between the periodontitis and control groups." (PMID 37927745, 2023). "In addition, flow cytometry also showed significantly decreased chemokine (CCR2 and CCL2) levels in gingival tissues from periodontitis mice in the StingGt group in comparison with that in the WT group (p < 0.001)." (PMID 37405166, 2023). "Also overrepresented in disease was the chemokine receptor gene CCR2, which, along with its corresponding ligand CCL2, is known to be involved in monocyte recruitment and tissue destruction in various oral diseases, including periodontitis." (PMID 36883648, 2023). "Building on these findings, we aimed to compare the frequency of a specific single nucleotide polymorphism (SNP) in the CCL2 gene between individuals with and without periodontitis." (PMID 37927745, 2023). "Treatment of both healthy and periodontally diseased gingival fibroblasts with pan-HDACi or HDAC3/6i prior to P. gingivalis infection significantly reduced the induction of a subset of inflammatory mediators (CCL2, CCL5, CXCL10, IL1B, COX2 and MMP3) implicated in periodontitis." (PMID 36291079, 2022). "Hence, we developed an experimental model of periodontitis in diabetic mice that can mimic the state of persistent CCL2 elevation in patients with DP." (PMID 32678310, 2021). "Furthermore, our group reported that salivary levels of CCL2 were diminished in aggressive periodontitis of the incisor-molar phenotype." (PMID 35048045, 2021). "However, other data reported that CCL2 levels were increased in the serum of patients with periodontitis, indicating that the role of CCL2 in periodontitis should still be addressed." (PMID 35048045, 2021). "This enhances the production of diverse inflammatory mediators, including IL-6, CXCL8, and CCL2, which may contribute to the overwhelming immune response and consequently to progression of periodontitis." (PMID 31178663, 2019). "The inflammatory potential of P. gingivalis HmuY has been shown, including induction of high levels of proinflammatory cytokines and CCL2, decreased levels of IL-8, and increased levels of anti-HmuY IgG and IgG1 antibodies in individuals with chronic periodontitis." (PMID 27403039, 2016).
periodontitis (continued). "On the one hand, the production of IL-6, CXCL8, and CCL2 might promote inflammatory response in periodontitis." (PMID 27504628, 2016). "For instance, attracted by chemokine (C–C motif) ligand 2 (CCL2) and other chemokines being highly expressed in gingival fibroblasts, macrophages infiltrate the connective tissue and contribute to innate immunity, particularly during periodontitis and peri-implantitis." (PMID 39781111, 2025). "In addition, our ligature-induced model confirmed the distinguished bone resorption and the pro-inflammatory gene expression of IL-1β, TNF-α, CCL-2, Nos2, IL-17 and IL-6, which were highly enhanced during the progress of the early acute phase of new periodontitis." (PMID 38069063, 2023). "In our study, we focused on the expression of three proteins, IL-6, CXCL8, and CCL2, which are thought to play an essential role in periodontal tissue inflammation and are usually regarded as the factors which enhance the inflammatory response in periodontitis." (PMID 31178663, 2019). "In our study, we observed that the levels of CCL2 and CCR2 were significantly decreased in StingGt periodontitis mice compared with WT periodontitis mice." (PMID 37405166, 2023). "This suggests that these monocytes are recruited by ligands of these receptors, in particular, CCL2, whose levels are elevated in GCF from patients with periodontitis." (PMID 38139161, 2023). "We found that the GCF samples obtained from periodontitis patients contained significantly higher proportions of cytokines such as TNF-α, CCL2, IL-6, IFN-γ, and CXCL8 compared to the samples obtained from systemically and periodontally healthy controls." (PMID 34502071, 2021). "GCF from periodontitis patients had significantly higher concentrations of TNF-α, CCL2, IL-6, IFN-γ, and CXCL8 than controls." (PMID 34502071, 2021). "TNF-α, CCL2, IL-6, IFN-γ, and CXCL8 showed significantly higher levels in GCF from periodontitis patients compared to control subjects (p < 0.05)." (PMID 34502071, 2021). "During the development of periodontitis, neutrophils release matrix metalloproteinase and proinflammatory cytokines including TNF-α, CCL2, and IL-6." (PMID 31781234, 2019). "BET inhibition significantly suppressed cytokine-induced mRNA expression of a broad range of inflammatory mediators involved in the pathogenesis of periodontitis, including IL8, IL1B, CCL2, CCL5, MMP3, and COX2." (PMID 31114581, 2019). "MCP-1 (CCL2), a chemokine involved in monocyte recruitment and amplification of local inflammation, was detected exclusively in the GCF of T1DM patients with periodontitis in our study (p < 0.05), supporting its role in periodontal immune responses." (PMID 41280935, 2025). "Moreover, PRF membranes increased chemokines CCL2, CCL7, CXCL2, and CXCL3, most of which are highly expressed in periodontitis fibroblasts." (PMID 39120336, 2024). "CCL2 was upregulated in both human and murine ICAM1+ fibroblasts, which was effectively reduced by lineage-specific deletion of Ikbkb thereby disrupting macrophage trafficking in the experimental periodontitis model." (PMID 39650645, 2024). "Our findings suggest that CCL2 and CCR2 may be involved in periodontitis progression by promoting macrophage recruitment, proinflammatory cytokine production and osteoclast formation." (PMID 37405166, 2023). "This pathway then drives the expression of interleukin 1 (IL1), IL6, and chemokines including chemokine (C-C motif) ligand 2 (CCL2), also referred to as monocyte chemoattractant protein 1, all of which are involved in chronic inflammation, such as periodontitis." (PMID 35209110, 2022). "We also measured the expression of CCL2 in the periodontium of nondiabetic mice with periodontitis (NP mice) and without periodontitis (N mice)." (PMID 32678310, 2021). "To investigate the kinetics of CCL2 production after the induction of periodontitis in diabetic and nondiabetic mice, we measured serum CCL2 levels in D and DP mice at various times." (PMID 32678310, 2021).
periodontitis (continued). "GFs could secrete IL-6 and CCL2 via activating TLR4 signaling, MAPK, and NF-κB pathways, resulting in the progression of periodontitis." (PMID 31608279, 2019). "CD14+ monocytes secrete a variety of cytokines, including TNF-α, IL-1β, IL-6, IL-8, CCL2, CCL3, and CCL5, compared to CD14− cells from GCF in patients with periodontitis, which suggests that CD14+ monocytes may be a source of CCL5 in GCF and gingival tissue in patients with periodontitis." (PMID 38139161, 2023). "NAMPT may contribute to periodontitis through upregulation of MMP-1 and CCL2 in PDL cells." (PMID 24058270, 2013).